ST6GAL1 (ST6 beta-galactoside alpha-2,6-sialyltransferase 1)
Diseases named in the same sentence as ST6GAL1 in open-access papers (continued):
Sharing a sentence is not in itself a finding about the gene and the disease.
multiple myeloma (3 papers, 2019 to 2022). "The exception is multiple myeloma, in which ST6Gal1 secreted by more mature B cells in the bone marrow suppressed myeloid development." (PMID 35371997, 2022). "In clinical multiple myeloma, ST6GAL1 abundance in the multiple myeloma cells negatively correlated with neutrophil abundance." (PMID 31408003, 2019). "ST6GAL1 mRNA expression was detectable in all cell lines except myeloma line RPMI 8226, with highest expression observed in the Burkitt lymphoma line Louckes." (PMID 31408003, 2019). "(A) Quantification of ST6GAL1 expression in bone marrow histological specimens from treatment-naive multiple myeloma patients (n = 15)." (PMID 31408003, 2019). "(C) Representative data from one patient with high and one patient with low myeloma ST6GAL1 expression, showing H and E with neutrophils indicated (left, arrows or arrowheads), and ST6GAL1 stain with myeloma cells indicated (right, arrowheads)." (PMID 31408003, 2019). "In bone marrow specimens of treatment-naïve human multiple myeloma, there was a striking negative association between marrow plasma cell ST6GAL1 expression and the prevalence of bone marrow neutrophils." (PMID 31408003, 2019). "Because of the clonal origin of multiple myeloma, the ST6GAL1 expression of the neoplastic plasma cell could be assessed." (PMID 31408003, 2019). "We observed that the abundance of segmented granulocytes within the marrow was strikingly and negatively associated with the level of ST6GAL1 expression, but not with the overall abundance of multiple myeloma plasma cells." (PMID 31408003, 2019). "The strong negative association between human multiple myeloma ST6GAL1 expression and neutrophil prevalence indicates that tumor-derived ST6GAL1 may dysregulate the development of bystander immune cells in the tumor microenvironment, with a variety of potential implications." (PMID 31408003, 2019).
pancreatic ductal adenocarcinoma (3 papers, 2018 to 2024). An infiltrating adenocarcinoma that arises from the epithelial cells of the pancreas. "The ST6GAL1 sialyltransferase is overexpressed in multiple cancers, including pancreatic ductal adenocarcinoma (PDAC)." (PMID 39260693, 2024). "Studies in rectal cancer and pancreatic ductal adenocarcinoma models have also reported that ST6Gal1 mediates chemoresistance via evading apoptosis through a mechanism that potentially involves TNFR1 sialylation." (PMID 36106023, 2022).
prostate tumours (3 papers, 2024). "We previously showed that ST6GAL1-mediated aberrant sialylation increases the growth of prostate tumours and is linked to disease progression." (PMID 38772281, 2024). "Next, we analysed a second 125 case TMA29 to compare ST6GAL1 levels in localised prostate cancer tumours and prostate tumours presenting with metastasis to bone or lymph node (all biopsy samples were taken from the primary site)." (PMID 38772281, 2024). "A common change in prostate tumour cell glycosylation is an increase in larger branched α2-6 sialylated N-glycans, driven by the sialyltransferase ST6GAL1." (PMID 38772281, 2024). "Our findings above suggest the levels of ST6GAL1 are also upregulated in aggressive prostate tumour tissue, however it is unclear whether the levels of blood borne ST6GAL1 are also higher in men with more aggressive disease." (PMID 38772281, 2024). "The data presented in this manuscript indicate that ST6GAL1-mediated aberrant sialylation could also be an important mediator of the acquired resistance of prostate tumours to enzalutamide therapy (which is a major clinical issue potentially affecting all men who develop CRPC." (PMID 39272811, 2024).
rectal cancer (3 papers, 2022 to 2024). A primary or metastatic malignant neoplasm that affects the rectum. "We showed that ST6GAL-1 mediates therapeutic resistance in rectal cancer by decreasing apoptosis and TNFR1 as the potential target of this decrease." (PMID 35041825, 2022). "We then used rectal cancer cell lines to further elucidate the role of ST6GAL-1 in resistance to chemoradiation." (PMID 35041825, 2022). "In this study, we investigated a novel role for ST6GAL-1 in therapeutic resistance in rectal cancer." (PMID 35041825, 2022). "We subsequently used rectal cancer cell lines to assess functional ST6GAL-1 protein after chemoradiotherapy and found that it was increased." (PMID 35041825, 2022). "In patient-derived xenograft models of rectal cancer, we found that ST6GAL-1 protein was increased after chemoradiation in a subset of samples." (PMID 35041825, 2022). "We also assessed changes in fluorescent staining of ST6GAL-1 (red) and Sia (green) after chemoradiation (3 μM 5-FU, 5 Gy radiation) in rectal cancer organoids and found that both were increased in the treated samples." (PMID 35041825, 2022). "We concluded that ST6GAL-1 promotes resistance to chemoradiotherapy by inhibiting apoptosis in rectal cancer cell lines." (PMID 35041825, 2022). "ST6GAL-1 knockdown in rectal cancer cell lines resulted in increased apoptosis and decreased survival after treatment." (PMID 35041825, 2022). "More research is needed to further elucidate the importance of ST6GAL-1-mediated resistance and its mechanism in human rectal cancer." (PMID 35041825, 2022). "Taken together, these studies implicate ST6GAL-1 as a potentially important mediator of resistance to chemoradiation in rectal cancer." (PMID 35041825, 2022). "Rectal cancer cell lines demonstrated increased ST6GAL-1 protein and cell surface Sia after chemoradiation." (PMID 35041825, 2022). "We also found that ST6GAL-1 appears to be subclonally expressed in individual rectal cancers via immunohistochemistry on our own patient samples." (PMID 35041825, 2022). "We generated and treated three patient-derived xenograft models of rectal cancer with chemoradiation and found that ST6GAL-1 protein was increased in two out of three of the models." (PMID 35041825, 2022). "We found that ST6GAL-1 and Sia on cell surface proteins are increased after chemoradiation in rectal cancer cell lines, rectal cancer–derived organoids, and PDX models using Western blot, flow cytometry, immunostaining, and immunoprecipitation." (PMID 35041825, 2022). "We also found that ST6GAL-1 was increased after treatment in primary rectal cancer organoids." (PMID 35041825, 2022). "We therefore hypothesized that ST6GAL-1 could mediate resistance to chemoradiation in rectal cancer by inhibiting apoptosis." (PMID 35041825, 2022). "ST6GAL-1 was also increased in rectal cancer organoids after treatment." (PMID 35041825, 2022). "In addition, while we have shown that ST6GAL-1 appears to likely alter radiation resistance via sialylation of proteins that mediate apoptosis in rectal cancer cell lines, but there are other possible mechanisms of resistance via sialylation or otherwise." (PMID 35041825, 2022). "In addition, we transduced rectal cancer cell lines with shRNA against ST6GAL-1 (knockdown [KD]) in order to study the effects of ST6GAL-1 on post-treatment cell survival and apoptosis." (PMID 35041825, 2022). "These prior studies did not assess rectal cancer cell lines or human tumors and did not assess the effects of chemoradiation; however, it appears likely that ST6GAL-1 is inhibiting apoptosis caused by chemoradiation via TNFR1." (PMID 35041825, 2022). "We also assessed whether ST6GAL-1 increases after treatment in rectal cancer organoids grown from primary rectal cancer tissue by both PCR and immunofluorescent staining." (PMID 35041825, 2022). "Consequently, we have shown that ST6GAL-1 may play a role in resistance to chemoradiotherapy in rectal cancer." (PMID 35041825, 2022).
rectal cancer (continued). "We have shown that ST6GAL-1 mediates resistance to chemoradiotherapy in rectal cancer cell lines and increases after treatment in some PDX and organoid rectal cancer models and that it is present in some untreated human rectal adenocarcinomas." (PMID 35041825, 2022). "Patient-derived xenograft and organoid models of rectal cancer and rectal cancer cell lines were assessed for ST6GAL-1 protein with and without chemoradiation treatment." (PMID 35041825, 2022). "ST6GAL-1 is likely not responsible for resistance in every rectal cancer, but our data show that it warrants further investigation." (PMID 35041825, 2022). "We did not assess ST6GAL-1 mRNA or protein in matched pre-versus-post treatment human rectal cancer specimens because of lack of availability of these specimens." (PMID 35041825, 2022). "Previous studies have shown that ST6GAL-1 is increased in various types of cancer, but the role of ST6GAL-1 in radiation resistance in rectal cancer has not been elucidated." (PMID 35041825, 2022). "Finally, we did not investigate whether ST6GAL-1 in pretreatment human rectal cancer samples correlates with increased ST6GAL-1 after chemoradiation or with increased ST6GAL-1-mediated resistance to chemoradiation." (PMID 35041825, 2022).
type 2 diabetes (3 papers, 2013 to 2023). "For example, an SNP in ST6GAL1, a gene encoding the β-galactoside α2,6-sialyltransferase, was associated with type 2 diabetes predisposition in Southeast Asians in a recent GWAS study, supporting growing evidence of the role of ST6GAL1 in inflammation." (PMID 35741825, 2022). "Interestingly, ST6GAL1 has been previously associated with Type 2 diabetes, MGAT3 with Crohn's disease, primary biliary cirrhosis and cardiac arrest, and FUT8 with multiple sclerosis, blood glutamate levels and conduct disorder." (PMID 23382691, 2013).
acute myelogenous leukemia (2 papers, 2015 to 2022). "who overexpressed ST6Gal1 in acute myelogenous leukemia cell lines and found decreased α4β1-mediated VCAM1 binding." (PMID 35371997, 2022).
benign meningioma (2 papers, 2021 to 2024). A grade I, slowly growing meningioma. "In the meningioma cell lines, mRNA expression of ST6GAL1 was highly expressed in the primary benign meningiomas—SUT-MG12 and SUT-MG14—while the mRNA expression of ST3GAL1 and ST3GAL3 was observed in the malignant meningioma cell lines—HKBMM and IOMM-Lee." (PMID 38274327, 2024). "High expression of ST6GAL1 in benign meningiomas may be involved in regulating benign tumor characteristics." (PMID 38274327, 2024). "ST6GAL1 was highly expressed in the primary benign meningioma cells—SUT-MG12 and SUT-MG14." (PMID 38274327, 2024). "In the benign meningioma cell line, glycation led to differences in expression of sialyltransferases (ST3GAL1/2/3/5/6, ST6GAL1/2, ST6GALNAC2/6, and ST8SIA1/2), which are known to play a role in tumor progression." (PMID 34943806, 2021).
brain cancer (2 papers, 2024). A primary or metastatic malignant neoplasm affecting the brain. "For instance, the upregulation of sialyltransferases ST6GAL1 has been linked to increased cancer cell aggressiveness, enhanced survival, and resistance to apoptosis in cancers such as breast, colon, prostate, and brain cancers." (PMID 39628991, 2024). "Research on glycosylation in brain cancer, particularly GBM, is limited but suggests a potential role for α2,6 sialylation and the enzyme ST6GAL1 in promoting GBM growth." (PMID 39628991, 2024).
brain tumor (2 papers, 2022 to 2024). "ST6GAL1 was identified as a key regulator of α2,6 sialylation in GBM, with higher expression observed in brain tumor-initiating cells (BTICs)." (PMID 39628991, 2024). "α2,6 Sialylation was regulated by ST6GAL1 in GBM, and ST6GAL1 was elevated in brain tumor-initiating cells (BTICs)." (PMID 36345944, 2022). "While our study has only explored the role of α2,6 sialylation and ST6GAL1 in BTICs in vitro and in immunocompromised mouse models, we acknowledge the potential importance of ST6GAL1 and/or ST6GAL2 in the brain tumor microenvironment." (PMID 36345944, 2022). "While ST6GAL1 is known to be important for N-glycan sialylation in the mouse brain, ST6GAL1/2 expression and function in the human brain or brain tumors have not been well characterized." (PMID 36345944, 2022). "While molecular effects of ST6GAL1 have not been well-studied in BTICs, studies in other tumor types have demonstrated sialylation of a select group of cell surface molecules that are known to play critical roles in brain tumors." (PMID 36345944, 2022).
chronic obstructive pulmonary disease (2 papers, 2019 to 2021). A chronic and progressive lung disorder characterized by the loss of elasticity of the bronchial tree and the air sacs, destruction of the air sacs wall, thickening of the bronchial wall, and mucous accumulation in the bronchial tree. "Here, we show that therapeutic administration of recombinant, bioactive ST6Gal-1 (rST6G) mitigates acute inflammation in a murine model mimicking acute exacerbations experienced by patients with chronic obstructive pulmonary disease (COPD)." (PMID 30778346, 2019).
Cognitive impairment (2 papers, 2017 to 2024). Abnormal cognition is characterized by deficits in thinking, reasoning, or remembering. "Furthermore, both CX3CR1 and ST6GAL1 have been linked to cognitive impairment." (PMID 39290304, 2024).
lung adenocarcinoma (2 papers, 2022 to 2024). A carcinoma that arises from the lung and is characterized by the presence of malignant glandular epithelial cells. "In a human lung adenocarcinoma model with cisplatin resistance, migratory capacity increased with ST6Gal1 and N-cadherin expression while E-cadherin expression was reduced." (PMID 36106023, 2022). "Only a handful of studies have focused on Ig-CAMs, including one pertaining to Necl in lung adenocarcinoma, where ST6Gal1 was identified as a target of mir-199a leading to reduction of Necl-2 sialylation." (PMID 36106023, 2022).
metastatic cancer (2 papers, 2019 to 2025). A carcinoma which has spread from the original site of growth to another anatomic site. "ST6GAL1 has been implicated in a variety of biological processes relevant to the development of disease, particularly in systemic inflammation and metastatic cancers." (PMID 31408003, 2019). "ST6GAL1 potential targets are proteins that are upregulated in metastatic cancer." (PMID 40938891, 2025).
non-small cell lung carcinoma (2 papers, 2021 to 2022). A group of at least three distinct histological types of lung cancer, including non-small cell squamous cell carcinoma, adenocarcinoma, and large cell carcinoma. "Similarly, in non-small cell lung cancer (NSCLC) cells, ST6GAL1 silencing suppressed migration and invasion in vitro and in vivo, through inactivation of the Notch1/Hes1/MMPs pathway." (PMID 33921986, 2021).
pancreatitis (2 papers, 2023 to 2024). Inflammation of the pancreas. "Moreover, SC mice form quantitatively more ADM-like cells during pancreatitis than WT mice, suggesting a causal role for ST6GAL1 in promoting inflammation-associated ADM." (PMID 37643018, 2023). "These combined effects of ST6GAL1 are expected to facilitate the survival of epithelial cells within the pancreatitis and PDAC microenvironments." (PMID 39260693, 2024). "Recently, our group discovered that ST6GAL1 is also upregulated during pancreatitis and functions within this context to promote acinar to ductal metaplasia (ADM)." (PMID 39260693, 2024). "We previously reported selective expression of ST6GAL1 in ADM-like cells during pancreatitis and established ST6GAL1 as a functional driver of ADM." (PMID 39260693, 2024). "Pancreatitis is a potent inducer of ADM; we therefore examined ST6GAL1 activity in the cerulein-stimulated pancreatitis model." (PMID 37643018, 2023). "Data herein show that endogenous ST6GAL1 is upregulated in the ADM-like cells induced by pancreatitis." (PMID 37643018, 2023). "Immunofluorescence staining for cytokines and ST6GAL1 revealed that ST6GAL1 was co-expressed with IL-1β and IL-6 in the epithelial cells of PDAC and pancreatitis tissues." (PMID 39260693, 2024). "No detectable SOX9 or ST6GAL1 was observed in healthy WT acinar cells (saline control), whereas numerous cells within WT pancreatitis tissues (cerulein) coexpressed amylase, SOX9, and ST6GAL1." (PMID 37643018, 2023). "In light of the known upregulation of ST6GAL1 during pancreatitis and PDAC, we postulated that ST6GAL1 expression may be regulated by cytokines present within the inflamed pancreas." (PMID 39260693, 2024). "Our results also point to a potential mechanism by which ST6GAL1 expression may be increased in nonmalignant acinar cells by inflammatory cytokines produced during pancreatitis." (PMID 39260693, 2024). "We speculate that, in the absence of pancreatitis, ST6GAL1 activity confers a progenitor-like state in which acinar cells have enhanced stem and ductal gene expression but have not yet adopted a ductal-like morphology." (PMID 37643018, 2023). "Importantly, the ectopic expression of ST6GAL1 in acinar cells induces a pronounced upregulation in a ductal gene network (in the absence of either pancreatitis or the KRAS oncogene), as evidenced by RNA-Seq results and staining of SC tissues for SOX9, KRT8, and KRT19." (PMID 37643018, 2023).
peritonitis (2 papers, 2019 to 2020). Inflammation of the peritoneum (tissue that lines the abdominal wall and covers most of the organs in the abdomen). "We observed in murine genetic models of circulatory ST6Gal-1 deficiency more pronounced peritonitis and airway acute inflammation elicited by sterile agents such as LPS." (PMID 30778346, 2019). "Additionally, deletion of St6gal1 enhances the neutrophilic and Th2 response in murine models of peritonitis and allergic pulmonary inflammation, respectively." (PMID 33166339, 2020).
rheumatoid arthritis (2 papers, 2018 to 2025). A chronic, systemic autoimmune disorder characterized by inflammation in the synovial membranes and articular surfaces. "Notably, B-cell Neu1 levels are strong predictors of remission as defined by two stringent remission criteria for rheumatoid arthritis (RA), whereas B-cell ST6Gal1 levels are associated only with remission status, as defined by the 2005 modified American Rheumatism Association (ARA) criteria." (PMID 40943151, 2025). "In this study, we firstly uncover that B-cell ST6Gal1/Neu1 ratios inversely forecast the combined remission and low-disease-activity subgroup with DAS28-MCP-12 ≤ 3.6 and SDAI ≤ 11 scores for rheumatoid arthritis." (PMID 40943151, 2025). "Therefore, the ST6Gal1/Neu1 ratio is a potential predictor for remission or combined remission and low disease activity for DAS28-MCP-1 and SDAI assessment in rheumatoid arthritis, pending confirmation by other studies." (PMID 40943151, 2025). "Nevertheless, there is still no publication to show the connection between ST6Gal1, Neu 1, or ST6Gal1/Neu1 ratios and disease activity of rheumatoid arthritis until now." (PMID 40943151, 2025).